MTOR (mechanistic target of rapamycin kinase)
Diseases named in the same sentence as MTOR in open-access papers (continued):
Sharing a sentence is not in itself a finding about the gene and the disease.
Obesity (continued). "Nonetheless, to what extent SR4 affects the mTOR pathway in these obese mice remains to be investigated, but targeting mTOR pathway may have some beneficial effects on obesity." (PMID 24376752, 2013). "The MTOR (mechanistic or mammalian target of rapamycin) pathway is activated by growth factors, hormones (such as insulin and testosterone), nutrients, oxygen and some conditions such as obesity." (PMID 23934728, 2013). "The mTOR pathway promotes obesity and is activated in obesity." (PMID 22267462, 2011). "High-calorie diet and obesity activate mTOR, thus promoting aging and cancer." (PMID 22267462, 2011). "For example, SIRT1 activation confers a therapeutic effect in type 2 diabetes, obesity and neurodegenerative diseases such as Alzheimer's and amyotrophic lateral sclerosis, whereas inhibition of mTOR is protective against cardiovascular and neurological diseases, diet-induced obesity and cancer." (PMID 20169165, 2010). "Considering that the mammalian target of rapamycin (mTOR) pathway plays a crucial role in determining the aging process, an increasing body of research has indicated that the mTOR pathway is hyperactivated in obesity, accentuating the aggravation of the aging process." (PMID 40566527, 2025). "The molecular pathogenesis of obesity-associated endometrial cancer involves complex dysregulation of key cellular signaling networks, with the phosphatidylinositol-3-kinase (PI3K)/AKT/mechanistic target of rapamycin (mTOR) pathway serving as a central mediator of malignant transformation." (PMID 41301707, 2025). "Therefore, targeting lipid metabolism or boosting autophagy through the AMPK/mTOR pathway could serve as potential therapeutic strategies for managing obesity-related depression." (PMID 39030618, 2024). "Besides animal studies, promising results come from in vitro studies, where extracts from some vegetables possess anti-obesity and anti-inflammatory properties, and also may block the activity of mTOR." (PMID 39200267, 2024). "Indeed, targeting the mTOR pathway has been suggested as a treatment for obesity." (PMID 37250653, 2023). "Recent studies showed that dietary polyphenols could target mTOR to reduce obesity." (PMID 36501200, 2022). "Therefore, it was speculated that mTOR signaling crosstalk might be a potential molecular mechanism linking obesity and OLF, which deserves further investigation." (PMID 35712246, 2022). "Thus, we can hypothesize that impaired leptin signaling in obesity and more specifically in NK cells might contribute to the dysregulation of the mTOR pathway." (PMID 36569860, 2022). "In addition, obesity-related acute pancreatitis is related to the PI3K/AKT/mTOR signaling pathway." (PMID 36671395, 2022). "Likewise, Huang and colleagues, presented evidence that identifying the therapeutic targets for AKT/PI3K/mTOR axis regulation may provide interesting options for obesity treatment." (PMID 35327652, 2022). "However, the downstream targets of mTOR that EA against obesity and the underlying mechanism are not been examined." (PMID 36313328, 2022). "However, chronic upregulation of mTOR activity can induce excessive protein and lipid synthesis as well as chronic downregulation of autophagy, which can contribute to several pathologies including cancer, obesity and cardiac/skeletal muscle degeneration." (PMID 34572128, 2021). "mTOR is a key pathway that regulates fundamental physiological processes, and could serve as a potential therapeutic target for the development of anti-obesity therapies, however, using direct mTOR inhibitors to lower lipogenesis may have adverse effects on homeostasis." (PMID 34722616, 2021). "Interestingly, placental mTOR protein levels have been correlated with early catch-up growth following FGR, which in turn may link mTOR-associated FGR to adverse metabolic outcomes, such as obesity, in childhood and beyond." (PMID 34828683, 2021). "Moreover, we demonstrated that SGLT2i suppressed mTOR activation in obesity mice." (PMID 32517059, 2020).
Obesity (continued). "Thus, a drug such as metformin that decreases circulating glucose and insulin levels, inhibits mitochondrial complex I, and disrupts the mTOR pathway may be useful in obesity- and mTOR pathway-driven cancers, such as OC." (PMID 29340030, 2017). "As total levels of mTOR and Raptor did not substantially change, we hypothesized that altered free Raptor reflected greater mTOR–Raptor association in aging or obesity." (PMID 26743335, 2016). "Therefore obesity-attributed hyperinsulinemia in Bif-1 KO mice may mediate the downregulation of Atg9 and Lamp1 through the activation of mTOR and suppression of TFEB signaling, and this hypothesis warrants further investigation in the future." (PMID 26857140, 2016). "In addition, obesity leads to hyperactivation of the mTOR pathway in epithelial tissues, suggesting that mTOR inhibitors may be a logical choice for treatment in obesity-driven cancers." (PMID 26959121, 2016). "Therefore, based on this evidence, we tested the hypothesis that diet‐induced obesity in pregnant mice activates the placental mTOR signaling pathway." (PMID 24744907, 2014). "Thus, it was not likely that pAKT or mTOR were dramatic regulators of obesity or weight loss-mediated tumor growth in this model." (PMID 25072025, 2014). "mTOR/pS6 was not regulated by obesity or weight loss in normal mammary or tumors." (PMID 25072025, 2014). "The mammalian target of rapamycin (mTOR) pathway may represent another important biological mechanism linking telomeric aging to obesity, because mTOR pathway integrates insulin and nutrient signaling in numerous cell types and enhanced mTOR signaling has been implicated in cellular senescence." (PMID 24861044, 2014). "Thus, the same pathway (such as mTOR) may be involved in aging, obesity and cancer per se, as well as aging and obesity can mutually stimulate each other (via the mTOR pathway) and both of them play causative role in cancer." (PMID 22267462, 2011). "Thus we concluded that rapamycin decrease obesity through its action on mTOR." (PMID 21593984, 2008). "In contrast, ULK1 Ser757 phosphorylation, a modification driven by mTOR that inhibits ULK1 activity, was elevated in aging with obesity but suppressed by DPR." (PMID 41549510, 2026). "The activation of the IGF1/PI3K/mTOR/S6K1 pathway mediates the formation of SGs and promotes the development of obesity‐related PDAC." (PMID 40211955, 2025). "In mice with obesity-induced muscle atrophy, administration of OJ extract increased the phosphorylation of PI3K, AKT, mTOR, and FoxO3a in gastrocnemius tissues." (PMID 41470891, 2025). "miR-200a-3p and miR-200b-3p, act as pro-obesity factors in vWAT-Exos, promote the lipid accumulation in adipocytes partially via PI3K/AKT/mTOR pathway." (PMID 40016734, 2025). "In cancer, obesity-induced expression of growth factors, inflammatory cytokines (e.g., IL-6 and TNF-α), and adipokines (e.g., leptin) can induce dysregulation PI3K/AKT/mTOR signaling pathway, to induce cancer progression and predict a poor prognosis." (PMID 40863244, 2025). "Clinical studies show reduced p-mTOR/mTOR in DKD, while podocyte mTORC1 hyperactivation in obesity CKD exacerbates renal dysfunction." (PMID 40337513, 2025). "Estrogen also amplifies mTOR outputs via IGF-1R upregulation, sustaining proliferative/survival programs that are accentuated in obesity-related endocrine milieus (increased aromatization, reduced SHBG)." (PMID 41301707, 2025). "Obesity and hyperglycaemia elevate insulin-like growth factor-1 (IGF-1) levels, driving oncogenic pathways such as PI3K/Akt/mTOR, which promote tumour proliferation and survival." (PMID 41002741, 2025). "Conversely, low circulating adiponectin in maternal serum, a feature of obesity and GDM, stimulates fetal growth by activating the placental insulin/IGF-1/mTOR signaling pathway." (PMID 40362828, 2025). "In humans with obesity, macrophage activation contributes to systemic low‐grade inflammation via the PI3K/mTOR pathway." (PMID 40742315, 2025).
Obesity (continued). "Obesity induces PPAR-driven lipid accumulation in NK cells and impairs the mTOR signaling pathway, inhibiting intracellular transport and leading to cytotoxic defects." (PMID 39402211, 2025). "mTOR inhibitors (e.g., rapamycin) and AKT inhibitors have been proposed to restore DDR efficiency and suppress tumor growth in obesity-driven cancers." (PMID 40282189, 2025). "Enhanced mammalian target of rapamycin (mTOR) signaling is demonstrated in pathologies, including T2DM and obesity." (PMID 39329975, 2024). "TMPs have been shown to be effective in reversing obesity induced by an HFD and promoting brown fat transformation by activating the AKT/mTOR pathway." (PMID 39408297, 2024). "The dysregulation of nutritional signaling, mediated by the IIS, sirtuins, mTOR, and mitogen-activated protein kinase (MAPK) pathways, is a key mechanism by which obesity impacts aging." (PMID 39044934, 2024). "Activation of POMC neurons suppresses appetite, whilst mTOR signaling in POMC neurons reduces POMC expression and triggers hyperphagia-induced obesity." (PMID 39063184, 2024). "A trend towards increased levels of survivin and a significant increase of phosphorylated mTOR and JNK were observed in pre-BS PBMCs of subjects with obesity versus the control counterpart." (PMID 39256343, 2024). "Both mTOR Ser2448 and mTOR Ser2481 levels were significantly increased only in VAT samples of subjects affected by obesity when compared to controls, and higher activation of mTOR was also observed in VAT versus SAT biopsies of individuals with obesity." (PMID 39256343, 2024). "Increased levels of phosphorylated mTOR and JNK were observed in PBMCs of subjects with obesity as compared to NW subjects." (PMID 39256343, 2024). "In an experimental model of obesity induced by a high-fat diet, it was observed that obesity impairs autophagy by inhibiting the phosphorylation of adenylate-activated protein kinase (AMPK) and promoting the phosphorylation of mTOR." (PMID 38026940, 2023). "The connection between obesity and cancer pathways via FTO seems to be regulated by mammalian target protein rapamycin (mTOR)." (PMID 35731272, 2023). "In the present study, we investigated the possible therapeutic effects of the flavonoid chrysin on obesity and NAFLD in rats, and the role of AMP-activated protein kinase (AMPK)/mammalian target of rapamycin (mTOR) pathways in mediating these effects." (PMID 36838721, 2023). "Through the activation of calpain or mTOR and inhibition of AMP-activated protein kinase (AMPK) in tissues, including heart and adipose tissue, obesity enhances pro-inflammatory response by decreasing autophagy flux." (PMID 37152942, 2023). "This obesity-promoting effect is mediated through Nras that is targeted by miR-29a-3p and is a negative regulator of the PI3K-Akt-mTOR pathway." (PMID 37761913, 2023). "In a high-fat diet (HFD)-induced obesity mouse model, 8 weeks of empagliflozin administration improved cardiac dysfunction via Sestrin2-mediated AMPK-mammalian target of rapamycin (mTOR) pathways by maintaining the redox stability." (PMID 35053290, 2022). "Recent studies have highlighted reduced AMP-activated protein kinase (AMPK) activity, increased mammalian target of rapamycin (mTOR) signaling, and mitochondrial dysfunction as shared pathobiology between ADPKD and overweight/obesity." (PMID 36106024, 2022). "Moreover, given that mTOR is essential for IL-15 signaling and consequently for NK cell development and activation, it can be assumed that obesity not only affects NK cell cytotoxic functions and antitumor activity but may also impact NK cell development and maturation." (PMID 36569860, 2022).
Obesity (continued). "Mechanistically, increased PA levels in plasma can induce liver PYCR1 expression to further inhibit the IRS-1/Akt/mTOR signalling pathway and thus exacerbate HFD-induced obesity and metabolic dysfunction." (PMID 36088469, 2022). "Diabesity, type 2 diabetes, and obesity alter many metabolic cascades, such as mitogen-activated protein kinase (MAPK), mammalian target of rapamycin (mTOR), and phosphoinositide-3-kinase/protein kinase B (PI3K/Akt), which has a systemic effect." (PMID 33995826, 2021). "Studies have proved that high level of BCAAs in plasma can continuously activate the mTOR signaling pathway and disassociate insulin receptor from insulin receptor substrate 1, which is closely related to the occurrence of T2DM and obesity." (PMID 34149613, 2021). "There are several mechanisms linking obesity and TNBC, including the role of insulin on the AKT/mammalian target of rapamycin (mTOR) signaling network, tissue inflammation, and protumorigenic tissue microenvironment driving the aggressive TNBC." (PMID 33935708, 2021). "Metformin, an inhibitor of mTOR, can protect SIRT1 activity to maintain proper circadian rhythm of CLOCK and BMAL1 during obesity." (PMID 34356626, 2021). "With obesity, overnutrition and alcoholic liver disease (ALD), mTOR is hyperactivated, resulting in persistent activation of SREBP-1 in the liver." (PMID 33363046, 2020). "It is a well-known fact that a high level of free fatty acids leads to constitutive activation of mTOR signaling, a pathway related to the advancement of conditions such as NAFLD and obesity." (PMID 32121602, 2020). "Therefore, we speculate that hypothalamic Tsc1 may regulate the feeding circuit via the mTOR signaling pathway, addressing the great significance to study the hypothalamic Tsc1-mTOR signaling pathway for better understanding the pathogenesis of obesity." (PMID 33532487, 2020). "Moreover, recent studies have found that elevated circulating free fatty acids may be an important factor in linking obesity and tumorigenesis, which can promote the proliferation and invasion of breast cancer cells through ERα signaling and the mTOR signaling pathway." (PMID 31440472, 2019). "The Lkb1-KO, mTOR-KO, mTORC1-KO, mTORC2-KO and Lkb1/mTOR DKO mice all display resistant to HFD-induced obesity 4,16,21." (PMID 30318987, 2019). "Obesity-responsive host characteristics interact with several cancer cell–intrinsic factors, including alterations in components of the PI3K/Akt/mTOR pathway, and metabolic characteristics." (PMID 28959684, 2017). "Over the last decade mTOR inhibitors, especially rapamycin, have shown promising effects on extending life- and health span in animal models of aging and obesity, effects that, at least for obesity, may be attributed to rapamycin's anti-inflammatory properties in the AT." (PMID 25979814, 2015). "TNF-α produced by obesity-induced inflammation stimulates IKK41, JNK42, and mTOR/S6K43, 44, which enhance serine phosphorylation of insulin receptor substrate-1 (IRS-1)." (PMID 26316333, 2015). "Adiponectin, another adipokine, downregulated in obesity, stimulates AMP-activated protein kinase (AMPK), which regulates energy homeostasis, and glucose metabolism by promoting catabolism and decreasing anabolism antagonistic to mTOR." (PMID 40696355, 2025). "Key pathways linking obesity and cancer include PI3K/Akt/mTOR and JAK/STAT3 activation." (PMID 41502515, 2025). "Anthocyanins, as natural bioactive compounds, hold significant promise in managing obesity and related metabolic disorders through their modulation of the PI3K/Akt signaling pathway and its downstream targets, such as GLUT4, FOXO, GSK3β, and mTOR." (PMID 40218884, 2025). "Together, these results strongly suggest that, for individuals exposed to aSDoH, obesity and hyperlipidemia promote NK cell dysfunction at least partially through pathways initiated by LDL involving Dusp1-mediated regulation of mTOR- and TFEB-facilitated lysosomal biogenesis." (PMID 39718832, 2024).
Obesity (continued). "A high-fat diet-induced obesity may suppress autophagy through the reduction of AMPK phosphorylation and the enhancement of mTOR phosphorylation, leading to depressive and anxiety-like behaviors in mice." (PMID 39030618, 2024). "Finally, a number of obesity-related miRNAs are also capable of regulating AMPK and mammalian target of rapamycin (mTOR), which trigger ROS-induced autophagy." (PMID 37672200, 2023). "How the impaired mTOR signalling contributes to energy homeostasis defects in SMS and the therapeutic potential of targeting this pathway to treat SMS-related obesity remains unclear and warrants future investigation." (PMID 37956053, 2023). "Developing drugs that specifically target key molecules in the molecular pathways connecting obesity and HCC, such as inhibitors of NF-κB, PI3K/AKT/mTOR, and PPAR-γ, may prove effective in preventing or treating HCC in obese individuals." (PMID 37834153, 2023). "In addition, mTOR is also involved in the transcription factors SREBPs, PPARγ/PPARα and TFEB in lipid metabolism, which is related to the development of tumours, obesity, and fatty liver." (PMID 36611986, 2023). "Obesity may affect the liver through different interrelated hepatic pathways that may include, adipokines, AMPK, mTOR, lipogenesis, and mitochondrial homeostasis." (PMID 36838721, 2023). "The discovery of the mTOR signaling pathway was of particular interest because the application of PI3K-Akt-mTOR signaling axis to COVID-19 disease and to other chronic conditions, such as obesity, has been reported." (PMID 35329141, 2022). "Moreover, during nutrient oversupply, phosphorylation of mTOR remains elevated, while that of S6K1 increases more in subjects with obesity compared to lean subjects." (PMID 35350688, 2022). "Our data revealed that deficiency in placental mTOR in utero shaped the adult female, but not the male, offspring’s adverse responses to HFD-induced obesity." (PMID 34032632, 2021). "Taken together with prior studies, these observations suggest a model whereby many of the metabolic effects of mTORC1 inhibition are likely mediated through activation of C/EBP-β, and that both mTOR and C/EBP-β are druggable targets to induce positive effects in the context of diet-induced obesity." (PMID 35822052, 2021). "According to Zhao and colleagues results, the protective role of obesity in premenopausal women could be favoured by activation of the AMPK signaling pathway and concomitant inhibition of proliferative stimuli via mTOR." (PMID 34485137, 2021). "Neither male nor female offspring with placental mTOR knockout developed obesity when subjected to a normal chow diet (18% kcal from fat) for 12-weeks." (PMID 34828683, 2021). "mTOR and its downstream target S6K1 are widely expressed in rat hypothalamus; mTORC1 overexpression in the hypothalamus can lead to changes in rats' feeding behavior and obesity occurrence." (PMID 33532487, 2020). "Furthermore, the elevation of KATP channel activity induced by increased mTOR signaling leads to hypertrophy of POMC neuronal cells, eventually developing aging-dependent obesity." (PMID 33776740, 2020). "Differently, the inhibited adipocyte differentiation and lipid accumulation induced by mTORC1 may explain the resistance to HFD-induced obesity in mTORC1, mTOR KO and LKB1/mTOR DKO mice 4,5,16." (PMID 30318987, 2019). "Through molecular classification, several target genes and molecular pathways in this tumor were identified, including DNA repair, hormone-related pathways, ERBB2/HER2, PI3K/AKT/mTOR signaling, the WNT pathway, immune-related pathways and obesity-driven targets." (PMID 30181460, 2018). "Reduced placental AMPK mRNA expression with GDM but not with obesity alone and suppression of gene expression for mTOR with obesity are indicative of complementary control mechanisms." (PMID 26513002, 2016). "Moreover, the constitutive activation of mTOR in the hypothalamus, specifically in POMC neurons, promotes food intake and obesity." (PMID 24040371, 2013).